CXCL10 (C-X-C motif chemokine ligand 10)
Diseases named in the same sentence as CXCL10 in open-access papers (continued):
Sharing a sentence is not in itself a finding about the gene and the disease.
cervical carcinoma (continued). "Additional experimental data showed that CXCL10 can inhibit the growth of cervical carcinoma through modulating the formation of micro-vessels and the expression of HPV oncoproteins E6 and E7." (PMID 34833360, 2021). "The HPV-positive (HPV+) cervical cancer cell lines SiHa and Caski secreted increased levels of CXCL10 compared to human foreskin fibroblasts (HFF-1), and its receptor CXCR3 was overexpressed in HFF-1." (PMID 34422627, 2021). "Another cytokine that has been studied as a possible therapy in cervical cancer is CXC chemokine ligand 10 (CXCL10)." (PMID 32455616, 2020). "They demonstrated that the combination of CXCL10 and radiotherapy effectively inhibited the growth of the cervical carcinoma cell line." (PMID 30345231, 2018). "Overall, these findings resulted in the conclusion that CXCL10 gene therapy in combination with radiotherapy is a novel effective therapeutic strategy for cervical cancer." (PMID 26622567, 2015). "The effects of CXCL10 gene therapy and radiotherapy alone and in combination on xenograft tumor models of cervical cancer were assessed in nude mice." (PMID 26622567, 2015). "In the present study, human HeLa cervical carcinoma tumors were established in immunodeficient mice, and CXCL10 gene therapy and radiotherapy were administered to establish the effects on tumor growth." (PMID 26622567, 2015). "Overall, CXCL10 gene therapy in combination with radiotherapy significantly inhibited cervical cancer tumor growth." (PMID 26622567, 2015). "In the present study, treatment with liposome-encapsulated CXCL10 gene therapy and radiotherapy was combined to assess the resulting inhibition of growth in cervical cancer tumors." (PMID 26622567, 2015). "Furthermore, this phenomenon was validated by analyzing the expression of CXCL8 and CXCL10 in both normal and cervical cancer tissues." (PMID 38275602, 2024). "With this in mind, our subsequent investigation delves into the intricate correlation between the expression levels of STING downstream genes, CCL5, CXCL9, and CXCL10, and their influence on the overall immune infiltration status within the cervical cancer TME." (PMID 38550593, 2024). "We can infer that CXCL10/CXCR3 axis and PD-1+CXCL10+ T cells may also play specific roles corresponding to their distribution in cervical cancer." (PMID 35847936, 2022). "Serum CXCL10 levels may be a novel and useful predictor for CESC as well as it can improve the diagnostic efficiency of SCC-Ag in prediction of cervical cancer." (PMID 36207693, 2022). "Accordingly, the prognosis of patients with a low CXCL10 expression in cervical cancer was poor." (PMID 34833360, 2021). "The results of this group also provide further evidence of the anti-tumor effects of CXCL10, which may be relevant in further exploration of the potential applications of this molecule in the treatment of cervical cancer." (PMID 34833360, 2021). "In addition, CXCL10 levels were significantly inversely correlated with vascular endothelial growth factor (VEGF) levels in cervical cancer." (PMID 34833360, 2021). "Furthermore, CXCL10 overexpression improved the radiosensitivity of tumors in a rodent cervical cancer model." (PMID 32582551, 2020). "Our previous study revealed that CXCL10 may induce apoptosis, inhibit angiogenesis and human papillomavirus, resulting in effects against cervical cancer." (PMID 26622567, 2015). "Furthermore, we identified that PRMT5 represses the expression of CXCL10 in cervical cancer cells." (PMID 41463372, 2025). "Collectively, these findings identify CXCL10 as a key chemokine upregulated upon PRMT5 deficiency, suggesting that PRMT5 may influence the recruitment of CD8+ T cells via the CXCL10 signaling pathway in cervical cancer." (PMID 41463372, 2025).
cervical carcinoma (continued). "Therefore, it was assumed that the combination of CXCL10 gene therapy and radiotherapy may improve the inhibition of cervical cancer progression through a variety of mechanisms, to achieve effective coordination in the treatment of cervical cancer." (PMID 26622567, 2015). "This study revealed that the presence of HPV16 and 18 oncogenes significantly alter the expression of CCL28, CXCL1, CXCL2, CXCL3, CXCL6, CXCL8, CXCL10, and CXCL11; overexpression of those chemokines was also confirmed in cervical cancer biopsies." (PMID 37893029, 2023). "Recombinant Syndecan 1 (SDC1) and CXCL10 were the two predicted genes and analysis of published works revealed that there were many reports of SDC1 in cervical cancer." (PMID 36207693, 2022). "In the current study, we focused on elucidating the novel mechanism of the PRMT5/CXCL10 axis in vivo, primarily utilizing mouse models and lacking a direct relevance to human cervical cancer." (PMID 41463372, 2025). "This demonstrated that PRMT5 knockdown induced an antitumor response through regulation of CXCL10 expression and suggested that PRMT5 inhibitors could serve as a promising therapeutic strategy for cervical cancer treatment." (PMID 41463372, 2025). "The combination of CXCL10 and SCC-Ag displayed significant improvement of AUCs than individual SCC-Ag or CXCL10 in the analysis groups (healthy vs all cervical cancer, healthy vs cervical cancer early stage)." (PMID 36207693, 2022). "Moreover, it has been also demonstrated that CXCL10 and its receptor CXCR3 were expressed by cervical cancer cells." (PMID 36207693, 2022). "Moreover, a general HDAC inhibitor, similar to SCFAs, also reduced CXCL10 release by IFN-γ-activated human colonic subepithelial myofibroblasts and cervical cancer cells (HeLa cells) and 2fTGH cells." (PMID 35409339, 2022). "We found CXCL10 expression negatively correlated with KDM5B expression in HPV+ head and neck cancer and positively correlated with STING expression in both HPV+ head and neck cancer and cervical cancer." (PMID 30080846, 2018). "Moreover, CXCL10 suppresses myeloma by recruiting effector CD8+ T, CD4+ T, and NK cells to the tumor site, and combining CXCL10 with radiotherapy enhances its therapeutic efficacy in cervical cancer." (PMID 37430270, 2023). "There was no other study of CXCL10 levels in cervical cancer patients." (PMID 36207693, 2022). "In addition, the secretion of CXCL10 was more apparent in HPV+ cervical cancer cells compared to non-infected and immortal epithelial cells." (PMID 34422627, 2021). "However, no data is available regarding serum CXCL10 levels in patients of cervical cancer to date." (PMID 36207693, 2022). "Moreover, CXCL10 showed ability in distinguishing cervical intraepithelial neoplasia from healthy control (AUCCXCL10 = 0.727) and cervical cancer SCC-Ag-negative from healthy control." (PMID 36207693, 2022).
autoimmune thyroiditis (33 papers, 2012 to 2025). "In thyroid tissues, secreted levels of CXCL10 are associated with T helper 1 (Th-1) cell infiltration which is commonly found in autoimmune thyroiditis and has been closely related to thyroid tumors." (PMID 29416784, 2018). "Higher serum levels of CXCL10 were found in a sample of 28 participants with psoriatic arthritis and autoimmune thyroiditis when compared to 37 participants with only psoriatic arthritis and 65 controls, suggesting a common path between both diseases." (PMID 37364143, 2023). "A previous study found that serum CXCL10 levels have been shown to be elevated in autoimmune thyroid diseases." (PMID 36266640, 2022). "CXCL10 plays a central role in thyroid autoimmune diseases, being involved, in the amplification of the Th-1-oriented immune response and ultimately in the recruitment of infiltrating lymphocytes expressing its receptor CXCR3." (PMID 34224085, 2021). "Increased CXCL10 was significantly associated with the presence of active vasculitis in HCV-associated cryoglobulinemia, or with autoimmune thyroiditis in CHC." (PMID 31485460, 2019). "A Th1 immune predominance has been shown in early PsO, and PsA, with high serum CXCL10 (Th1 prototype chemokine), overall in the presence of autoimmune thyroiditis." (PMID 28674524, 2017). "Furthermore, a significantly higher level of CXCL10 has been found in psoriatic arthritis with autoimmune thyroid diseases than psoriatic arthritis alone." (PMID 31157131, 2019). "Interestingly, serial measurements of serum CXCL10 has been correlated with persistence or resolution of autoimmune thyroid disease, which is seen frequently with sarcoidosis." (PMID 24199653, 2013). "Newly diagnosed autoimmune thyroiditis patients demonstrate increased serum CXCL-10 levels." (PMID 23316383, 2012). "Additional chemokines, such as CXCL10, CXCL9, CCL2, and CCL22, are expressed in both psoriatic and thyroid autoimmune diseases." (PMID 40863211, 2025). "These chemokines play an important role in the pathogenesis of thyroid autoimmune diseases, and studies have shown that IFN-γ induces the secretion and expression of CXCL10, CXCL9 and CXCL11 in a dose-dependent manner." (PMID 38567309, 2024). "Precisely these cytokines, such as IFN-alpha, IFN-gamma, and CXCL10/IP10, peculiar of Th1-type immune response, play a crucial role in the pathogenesis of autoimmune thyroid diseases, including GD and Graves’ ophthalmopathy (GO)." (PMID 36146523, 2022). "In autoimmune thyroid disease, IFN-γ and TNF-α were consistently reported to synergize in the induction of the chemokine CXCL10 secretion by thyrocytes." (PMID 34224085, 2021). "In the same time, autoimmune thyroid diseases including Hashimoto’s thyroiditis are Th1 immune-mediated disorder, in which Th1 cells, IFN-gamma with its dependent chemokines including CXCL10 play an important role." (PMID 31157131, 2019). "Growing amount of evidence indicate that IFN-ɣ inducible chemokines (CXCL9, CXCL10 and CXCL11) and CXCR3 (their main receptor) play an important role in the initial stage of autoimmune thyroiditis." (PMID 29416784, 2018).
lung disease (33 papers, 2005 to 2025). "AMP5A treatment of innate immune cells results in a significant decrease in CXCL10 release as well as inhibition of a slew of pro-inflammatory mediators linked to hyperinflammation and lung disease." (PMID 35261923, 2022). "CXCL10 is associated with the pathogenesis of lung diseases, including BPD and IPF." (PMID 37876024, 2023). "CXCL10, a chemokine attracting immune cells to infection sites, is elevated in severe pulmonary disease patients’ serum and bronchoalveolar lavage fluid, positively correlating with disease severity." (PMID 40164948, 2025). "CXCL10 is an important regulator of pulmonary diseases, and has the function of chemotactic monocytes/macrophages, T cells, and NK cells and promotion of T-cell adhesion to endothelial cells." (PMID 31656701, 2019). "Considerable evidence indicates the importance of CXCL10 in antiviral host defense but also in development or prevention of certain lung diseases." (PMID 23497334, 2013). "By contrast, lung disease in MRLlpr mice involves the recruitment of CXCR3 positive T cells via local secretion of CXCL10, and the endothelial expression of selectins and intercellular adhesion molecule (ICAM)-1." (PMID 21637713, 2011). "The CXCL10 level was found to be increased in the plasma of untreated and treatment-refractory patients with Mycobacterium avium complex (MAC)-induced lung diseases, suggesting a role of CXCL10 as a marker of NTM disease." (PMID 32155958, 2020). "A number of studies have shown that CXCL10 and its receptor CXCR3 are involved in the regulation of inflammatory, angiogenic and fibrotic processes also in human lung diseases." (PMID 27428020, 2016). "CXCL10 participates in monocyte, neutrophil, and lymphocyte recruitment and significantly contributes to the progression of COPD disease state, which may present as a therapeutic target of AT-RvD1 in dust-induced lung disease." (PMID 39776904, 2024).
pulmonary TB (33 papers, 2010 to 2026). "In this study, the PD-L1(Programmed Death Ligand-1), EN-RAGE (Extracellular Newly Identified RAGE-Binding Protein), and CXCL10 (Chemokine C-X-C Ligand 10) have significant diagnostic value for severe pulmonary TB." (PMID 40164948, 2025). "Conversely, it was noted that CXCL10 appeared to have higher diagnostic utility in pulmonary TB than in the current study." (PMID 34868023, 2021). "Up-regulation of NRF in the PBMC of active pulmonary TB patients with high bacterial load is associated with increased occupancy of NRF at the IP-10/CXCL10 and IL-8/CXCL-8 promoters and decreased the synthesis of corresponding mRNA." (PMID 24223729, 2013). "Cxcl10 is widely considered an essential inflammatory mediator in various inflammation-associated diseases, such as ulcerative colitis, non-alcoholic steatohepatitis, pulmonary tuberculosis (Ali, Mankhi & Ad’hiah, 2021), and non-alcoholic steatohepatitis." (PMID 39677961, 2024). "Our data shows that interleukin-27 and CXCL10 are significantly related in pulmonary tuberculosis, and has-let-7b-5p and has-miR-30a-3p are also related to interleukin-27 and CXCL10." (PMID 35785034, 2022). "We have now demonstrated that NRF is upregulated in the circulating monocytes and AM of patients with active pulmonary TB, and modulates synthesis and release of IP-10/CXCL10 and IL-8/CXCL8." (PMID 24223729, 2013). "Patients with active pulmonary TB had a higher serum level of IP-10/CXCL10 (392.2±70.5 pg/ml, n = 19) and IL-8/CXCL8 (31.9±8.5 pg/ml, n = 19) than that of normal subjects (62.8±5.4 pg/ml; 4.5±.0 pg/ml, n = 15, p<0.01, respectively)." (PMID 24223729, 2013). "In summary, we demonstrated that NRF, for the first time in human disease, is up-regulated in the PBMC and AM of active pulmonary TB patients with high bacterial load to repress MTb induced IP-10/CXCL10 and IL-8/CXCL8 synthesis and protein release." (PMID 24223729, 2013). "We delineate the role of NRF in pulmonary TB, which inhibits the expressions of IP-10/CXCL10 and IL-8/CXCL8 in AM and PBMC of patients with high bacterial load." (PMID 24223729, 2013). "Notably, CXCL10 levels significantly increase in patients with severe pulmonary tuberculosis." (PMID 40164948, 2025). "The CXCL10 (IP-10) level was found to be decreased in the course of a 6-month-long anti-TB therapy and could be a useful indicator in identifying and monitoring the progression of pulmonary TB as well as the efficiency of therapeutic interventions." (PMID 36164329, 2022). "Our results indicate a pathophysiological role of NRF in repression of IP-10/CXCL10 and IL-8/CXCL8 synthesis by AM and PBMC in active pulmonary TB." (PMID 24223729, 2013). "Increased release of chemokines, including IL-8/CXCL8, IP-10/CXCL10, MIG/CXCL9 and MCP-1/CCL2, has been observed in monocytes, alveolar macrophages and polymorphonuclear granulocytes in patients with pulmonary TB compared to healthy subjects." (PMID 24223729, 2013). "Levels of IP-10/CXCL10 and IL-8/CXCL8 mRNA were higher in AM from patients with AFB-high active pulmonary TB (9.8±1.9, p<0.01 and 0.3±0.2, p<0.01, n = 6, respectively) than those of normal subjects (0.3±0.1 and 0.1±0.01, n = 8, respectively)." (PMID 24223729, 2013). "Knockdown of NRF by NRF siRNA augmented the mRNA synthesis and protein release of both IP-10/CXCL10 and IL-8/CXCL8 from PBMC of active pulmonary TB patients with high bacterial load." (PMID 24223729, 2013). "The up-regulated release of IP-10/CXCL10 and IL-8/CXCL8 in patients with active pulmonary TB was suppressed by specific NF-κB inhibitor JSH-23, suggesting both IP-10/CXCL10 and IL-8/CXCL8 release is mediated through NF-κB activation." (PMID 24223729, 2013). "IP-10/CXCL10, which is induced either by IFN-γ, IFN-β or virus has been reported to increase in pulmonary TB, which we also observed." (PMID 24223729, 2013).
pulmonary TB (continued). "The levels of IP-10/CXCL10 and IL-8/CXCL8 mRNA from PBMC were significantly higher in patients with AFB-high active pulmonary TB (0.2±0.1, n = 6, p<0.01 and 3.0±0.8, n = 6, p<0.001, respectively) as compared with normal subjects (0.001±0.001 and 0.3±0.1, n = 8, respectively)." (PMID 24223729, 2013). "Patients with AFB-low active pulmonary TB had a higher level of IP-10/CXCL10 mRNA (0.05±0.03, n = 6, p<0.01), but not IL-8/CXCL8 (0.5±0.2, n = 6) than normal subjects." (PMID 24223729, 2013). "Patients with AFB-low active pulmonary TB had a higher level of IL-8/CXCL8 mRNA (0.2±0.03, n = 6, p<0.05), but not IP-10/CXCL10 mRNA (0.5±0.2, n = 6) than normal subjects." (PMID 24223729, 2013).
SARS-CoV infection (33 papers, 2007 to 2023). "In a MERS-CoV infection, the epithelial and endothelial cells induced significant but delayed IFN and pro-inflammatory cytokine (IL-1β, IL-6 and IL-8) responses, while a large quantity of CCL3, CCL5, CCL2, and CXCL10 was produced during a SARS-CoV infection." (PMID 36016187, 2022). "Despite an abortive infection, the SARS-CoV infection in human macrophages induced the expression of a number of proinflammatory chemokines including IP-10/CXCL10 and MCP-1/CCL2." (PMID 26690369, 2015). "In severe cases of SARS-CoV infection, however, CXCL10 levels remained significantly elevated for the duration of the patient’s infection." (PMID 23029269, 2012). "However, while CXCL10 is protective in SARS-CoV infection, its precise role in H1N1pdm09 infection is unclear." (PMID 32599823, 2020). "As compared to the SARS-CoV infection, MERS-CoV infection induced significantly higher expression levels of IL-8, IL-12, IP-10/CXCL-10 and MCP-1/CCL-2." (PMID 34876129, 2021). "SARS-CoV infection of myeloid dendritic cells, even unproductive, leads to chemokines upregulation of CXCL10 (IP-10), CCL2 (MCP-1), CCL3 (MIP-1a) and CCL5 (RANTES)." (PMID 32962761, 2020). "As a result of miRNA-223 inhibition, mRNA expression levels of NLRP3 inflammasome and pro-inflammatory chemokines CXCL10, CXCL2, and IL-1ß were increased, suggesting a contribution of miR-223-3p in vivo to limit excessive lung inflammation induced by SARS-CoV infection." (PMID 35229638, 2022). "Another chemokine, Interferon-inducible protein-10 (IP-10; also known as CXCL10) detected in SARS-CoV infections might be critical since its expression levels was shown to be associated with disease severity in SARS-CoV-2 patients." (PMID 32850752, 2020). "Similarly, DUSP8, IL6, CXCL10, and NFKBIA are up-regulated in SARS patients, while PTX3 and CXCL2 have been shown to be involved in SARS-CoV infection." (PMID 23935999, 2013). "In particular, early enhanced expression of interferon-inducible protein-10 (CXCL-10) and monocyte chemoattractant protein-1 (MCP-1) have been correlated with an adverse outcome during SARS-CoV infection in humans, which was also highly upregulated in this study." (PMID 21533129, 2011). "Lung autopsies of SARS patients and in vitro SARS-CoV infections of macrophages and alveolar and bronchial cells have clearly demonstrated upregulation of numerous monocyte/macrophage, neutrophil and T cell-specific chemokines, including CCL2, CCL5, CXCL8, CXCL9 and CXCL10." (PMID 33613280, 2020). "Immune cell—recruiting chemokines and cytokines, such as IP-10/CXCL-10, MCP-1/CCL-2, MIP-1α/CCL-3, RANTES/CCL-5, can be strongly induced by MERS-CoV, showing higher inducibility in human monocyte—derived macrophages by MERS-CoV as compared to than SARS-CoV infection." (PMID 32522207, 2020). "Two IFN-induced chemokines, CCL2 and CXCL10, were significantly upregulated in the lung at 5–7 DPI with SARS-CoV infection but not after reinfection." (PMID 23029269, 2012).